LINC00698 (long independently transcribed non-coding RNA 698)
Gene: Long non-coding RNA gene on chromosome 3 (62,950,384 to 63,148,804, forward strand). Ensembl gene ENSG00000244342.
Diseases named in the same sentence as LINC00698 in open-access papers:
LINC00698 is named in the same sentence as 2 diseases in open-access papers, as found by Europe PMC text mining. Sharing a sentence is not in itself a finding about the gene and the disease. The quoted sentences say what the papers report.
melanoma (1 paper, 2024). A malignant, usually aggressive tumor composed of atypical, neoplastic melanocytes. "The results showed that LINC00698 was significantly upregulated in MSCs compared with MNSCs, suggesting that LINC00698 was associated with melanoma tumorigenesis." (PMID 39068483, 2024). "Among them, LINC00698 was significantly upregulated in melanoma based on the MiTranscriptome database." (PMID 39068483, 2024). "Collectively, these findings revealed that LINC00698 was upregulated in MSCs, suggesting its important role in melanoma progression." (PMID 39068483, 2024).
tumor (1 paper, 2025). "Under vitamin D monotherapy, NK cells showed suppression of pathways associated with tumor-promoting signaling, including genes, such as FGF19 and LINC00698." (PMID 41515234, 2025).